SHANK3 (SH3 and multiple ankyrin repeat domains 3)
Description:
Major scaffold postsynaptic density protein which interacts with multiple proteins and complexes to orchestrate the dendritic spine and synapse formation, maturation and maintenance. Interconnects receptors of the postsynaptic membrane including NMDA-type and metabotropic glutamate receptors via complexes with GKAP/PSD-95 and HOMER, respectively, and the actin-based cytoskeleton. Plays a role in the structural and functional organization of the dendritic spine and synaptic junction through the interaction with Arp2/3 and WAVE1 complex as well as the promotion of the F-actin clusters. By way of this control of actin dynamics, participates in the regulation of developing neurons growth cone motility and the NMDA receptor-signaling. Also modulates GRIA1 exocytosis and GRM5/MGLUR5 expression and signaling to control the AMPA and metabotropic glutamate receptor-mediated synaptic transmission and plasticity. May be required at an early stage of synapse formation and be inhibited by IGF1 to promote synapse maturation.
Synonyms: ProSAP2; KIAA1650; PSAP2; SPANK-2; DEL22q13.3; SCZD15
Gene: Protein-coding gene on chromosome 22 (50,674,408 to 50,733,212, forward strand). Ensembl gene ENSG00000251322.
Subcellular location: Cytoplasm; Postsynaptic density; Cell projection, dendritic spine
Subcellular location (Human Protein Atlas): Nucleoplasm; Plasma membrane
Genetic constraint (gnomAD): Loss-of-function variants: 27 observed, 83.48 expected, observed/expected ratio (o/e) 0.32, 90% interval 0.24 to 0.45. The synonymous counts are far from expectation, so gnomAD's model fits this gene poorly and the ratio says little. Missense variants: 2,020 observed, 1,857.7 expected, observed/expected ratio (o/e) 1.09, 90% interval 1.05 to 1.13. Synonymous variants: 1,264 observed, 877.19 expected, observed/expected ratio (o/e) 1.44, 90% interval 1.38 to 1.51.
Gene-disease validity (ClinGen):
ClinGen rates the evidence that SHANK3 causes each of these diseases.
Phelan-McDermid syndrome (autosomal dominant): Definitive.
Homologues: Orthologues: chimpanzee SHANK3 (95% identical), macaque SHANK3 (95% identical), rat Shank3 (95% identical), dog SHANK3 (92% identical), mouse Shank3 (92% identical), guinea pig SHANK3 (89% identical), tropical clawed frog shank3 (64% identical), zebrafish shank3b (54% identical), zebrafish shank3a (52% identical), Drosophila melanogaster Prosap (21% identical), Caenorhabditis elegans shn-1 (18% identical). Paralogues in human: SHANK2 (46% identical), SHANK1 (40% identical).
Diseases named in the same sentence as SHANK3 in open-access papers:
SHANK3 is named in the same sentence as 148 diseases in open-access papers, as found by Europe PMC text mining. Sharing a sentence is not in itself a finding about the gene and the disease. The quoted sentences say what the papers report.
autism (275 papers, 2009 to 2026). Persistent deficits in social interaction and communication and interaction as well as a markedly restricted repertoire of activity and interest as well as repetitive patterns of behavior. "Similar findings were observed by others, namely, increased D2 receptor binding density in the ventral striatum in Shank3-deficient mice, and a similar trend was observed in the Fmr1 mouse model of autism." (PMID 39654001, 2025). "Pharmacological inhibition of the Erk pathway effectively restored oligodendrocyte maturation in vitro, rescued myelination deficits in vivo, and partially improved autism-related behaviors and motor function in Shank3-deficient mice." (PMID 41203933, 2025). "This significantly reduces the expression of GKAP and PSD95, key molecules of the SHANK3 signaling pathway, causing autism in rats." (PMID 39997934, 2025). "Shank3, in particular, has been repeatedly linked to neurodevelopmental disorders, most prominently autism." (PMID 41226815, 2025). "Mutations in SHANK3 are associated with Phelan-McDermid syndrome (22q13.3 deletion) and autism, due to symptoms such as impaired social interaction and repetitive behaviors observed in animal models." (PMID 40519825, 2025). "Mutations of the SHANK family genes (SHANK2 and SHANK3) have been associated with autism pathophysiology." (PMID 40868063, 2025). "The reduction in the number of GABAergic neurons in the hippocampus of both autism-like animal models corresponds to our previous findings demonstrating reduced GAD65/67 expressions in the brains of Shank3-deficient mouse pups and adults." (PMID 41166021, 2025). "Mutations in Shank3 have been extensively validated in rodent models, where they are linked to autism‐like phenotypes, including impaired social interactions." (PMID 40755426, 2025). "Among the genes implicated in ASD, SHANK3 has received significant attention due to its strong association with autism, schizophrenia, and intellectual disability." (PMID 40755426, 2025). "The striatum is a brain region important for stereotypic behaviors, which was found to be defective in Shank3-deficient autism mouse models." (PMID 41301465, 2025). "Another patient with an isolated SHANK3 deletion presented with neurodevelopmental delay, language impairment, autism, and craniofacial features typical of SHANK3-associated Phelan-McDermid syndrome." (PMID 40626178, 2025). "To define the electrophysiological properties of neurons in our autism-associated dog model, we prepared acute brain slices from Shank3 heterozygous mutants (Mut) and wild-type (WT) dogs, and maintained slices under consistent perfusion in aCSF." (PMID 38297387, 2024). "Using CRISPR/Cas9 editing, we recently generated a dog model carrying Shank3 mutations, which displayed a spectrum of autism-like behaviors, such as social impairment and heightened anxiety." (PMID 38297387, 2024). "Autism associated with disruption of SHANK3 results from a variety of different genetic perturbations, but most commonly from 22q13 deletions (simple deletions and, less commonly, ring chromosome and unbalanced translocations)." (PMID 38352654, 2024). "Numerous studies support a strong genetic component in the development of autism, with links to mutations involving specific genes such as SHANK3, NLGN3, and NRXN1." (PMID 38435203, 2024). "Our electrophysiological data also confirm that the inhibition of GABAARs leads to increased synaptic activity of striatal neurons from Shank3-deficient mice, highlighting the well-known excitation/inhibition imbalance in the context of autism." (PMID 39334399, 2024). "Dogs carrying autism‐linked Shank3 mutations display impaired neural coupling and attention, which are rescued by the psychedelic lysergic acid diethylamide." (PMID 39257367, 2024).
autism (continued). "In the study, the selective ablation of the autism-risk gene Shank3 in ACC pyramidal neurons caused social interaction deficits while restoration of Shank3 only in ACC neurons rescued social deficits in global Shank3 mutant mice." (PMID 38576034, 2024). "This study aimed to elucidate the role of the Shank3 gene, known to be associated with monogenic causes of autism, in early developmental processes to inform the timing and mechanisms for potential interventions for ASD." (PMID 39693031, 2024). "More importantly, Shank3 has been identified as one of the few genes whose mutations can lead to autism." (PMID 38676295, 2024). "To date, the underlying mechanisms by which Shank3 mutation or deletion causes autism and the part of the brain in which Shank3 mutation leads to the autistic phenotypes are understudied." (PMID 38570876, 2024). "Congruently, prior evidence in autism, rare genetic conditions linked to autism (eg, Fragile X), and autism rodent models (eg, SHANK3 gene) has linked altered brain development to various genes, including those regulating synaptic development." (PMID 39412777, 2024). "KIF1A and SHANK3 are enriched in neural tissues and are associated with neurodevelopmental disorders such as autism, epilepsy, or spastic paraplegia." (PMID 38370698, 2024). "SH3 and multiple ankyrin repeat domains protein 3 (SHANK3) monogenic mutations or deficiency leads to excessive stereotypic behavior and impaired sociability, which frequently occur in autism cases." (PMID 38570876, 2024). "Mutations within the SHANK3 gene or SHANK3 haploinsufficiency is thought to be one of the major causes for Phelan-McDermid Syndrome (PMDS) that is characterized by a broad spectrum of autism-related behavioral alterations." (PMID 36355061, 2023). "Mutations in SHANK3 are estimated to occur in 1–2% of people with autism and intellectual disabilities, while mutations in SHANK1 and SHANK2 are less common." (PMID 36846568, 2023). "Strong comorbidity between features of autism features and catatonia or a singular disorder more fundamentally linked to SHANK3 mutations?" (PMID 37810596, 2023). "For instance, the simultaneous downregulation of both Shank2 and Shank3 proteins was recently shown to impair social memory, a feature strictly associated with autism." (PMID 37019889, 2023). "Studies have shown that SH3 and multiple Ankyrin repeat domains 3 (SHANK3) -deficient mice, a model of autism, had significantly lower levels of GABA synthesis in the hypothalamus and VTA compared to controls." (PMID 37200906, 2023). "Remarkably, these SH3-binding site are essential to the autism-mutated SH3 and multiple ankyrin repeat domains protein 3 (SHANK3) protein." (PMID 36945042, 2023). "SHANK3 mutations are detected in 1–2% of patients with autism and intellectual disability, identifying the deletion or inactivation of one copy of this gene as a major cause of neurodevelopmental disorders." (PMID 38002499, 2023). "Using human telencephalic organoids generated from stem cell-derived single neural rosettes, Wang and coworkers have analyzed brain organoids carrying a hemizygous deletion of an autism- and intellectual disability-associated gene SHANK3." (PMID 37759640, 2023). "In conclusion, this study demonstrated that 8 weeks of swimming is effective in improving the behavioral phenotype related to autism comorbidity and promotes the growth of neurons and the expression of related proteins in Shank3‐deficient rats." (PMID 36221783, 2023). "Shank3-dependent molecular, structural, and functional changes of excitatory synapses have been characterized from preclinical in vivo studies in a complete KO mouse model of the autism-associated Shank3 gene, underlying pathophysiological mechanisms." (PMID 36831241, 2023). "Further the NRXN-NLGN-SHANK pathway has been associated with E/I balance, and NRXN1 and SHANK3 deletions have both been implicated in autism." (PMID 37441676, 2023).
autism (continued). "Shank3 is a recognized autism risk gene, and detailed mechanismic research provides insight into its role in drosophila, mice, rats, monkeys, and other species." (PMID 36221783, 2023). "For example, multiple autism-associated synaptic proteins, including Nlgn3, Shank3, and FMRP, affect group-I or group-5 metabotropic glutamate receptors (mGluRs)." (PMID 35601025, 2022). "Related to this model, two mutations in SHANK3 (R12C and L68P) linked to autism have been studied for their consequences on its scaffolding function." (PMID 36273588, 2022). "SHANK3 is a high confidence autism risk gene that encodes a prominent excitatory postsynaptic scaffold protein." (PMID 36038911, 2022). "Our results support the observation that autism-associated SHANK3 protein isoforms seem to be critical in inducing synaptic plasticity following mTBI." (PMID 35682760, 2022). "It has been previously shown that Shank3 mutations in humans predispose to autism by inducing a channelopathy." (PMID 35022531, 2022). "We then demonstrated its usefulness for identifying modified social vocalizations in animal models of neurodevelopmental diseases by revealing impaired social communications in adult male Shank3-deficient rats, a rat model of autism." (PMID 35820848, 2022). "The authors generated human brain organoids from stem cell-derived isolated single neural rosettes to study human cortico-striatal development and deficits caused by an autism-associated genetic abnormality in SHANK3." (PMID 36202854, 2022). "A recent study has also identified an autism-linked missense mutation in SHANK3 that causes defects in Shank3 recruiting a number of actin-binding proteins to the PSD, leading to the disruption of spine development." (PMID 36245917, 2022). "Abnormalities within the three SHANK genes are detected in the whole spectrum of autism and a higher cognitive impairment is observed when mutations are present in the SHANK3 and SHANK2 genes compared to SHANK1." (PMID 36100669, 2022). "This is in line with the present observation on the upregulation of RPL36A in autistic patients and indicates that the upregulation of RPL36A can influence the development of autism through the dysfunction of SHANK3-associated synaptopathies." (PMID 35215271, 2022). "Heterozygous mutation or chromosomal loss of SHANK3 is causative of Phelan–McDermid syndrome, a severe neurodevelopmental condition associated with autism and sleep disruption." (PMID 36038911, 2022). "While heterozygous SHANK3 mutations are usually the types of mutations associated with idiopathic autism in patients, heterozygous deletion of Shank3 gene in mice does not commonly induce ASD-related behavioral deficit." (PMID 35022531, 2022). "Based on previous results showing neurodevelopmental delay in children with autism, we expected to observe a similar phenotype in animals with the Shank3 gene mutation." (PMID 35884680, 2022). "We also demonstrate that neurons in organoids with a hemizygous deletion of an autism- and intellectual disability-associated gene SHANK3 exhibit intrinsic and excitatory synaptic deficits and impaired expression of several clustered protocadherins." (PMID 36202854, 2022). "We then employed TrackUSF to analyze social vocalizations in Shank3-deficient rats, a rat model of autism, and revealed that these vocalizations exhibit a spectrum of deviations from appetitive calls towards aversive calls." (PMID 35820848, 2022). "SAXS and thermal stability assays revealed that both autism mutations alter the overall structure, stability, and conformational flexibility of SHANK3." (PMID 36273588, 2022). "Defects in the SH3 and multiple ankyrin repeat domains 3 (Shank3) protein cause numerous synaptopathies, including autism; upregulation of the RPL36A was reported in the striatal synaptosome of Shank3-overexpressing transgenic mice." (PMID 35215271, 2022).
autism (continued). "More importantly, it remains to be clarified how individual missense mutations in the N-terminal part of Shank3 lead to neurodevelopmental disorders, such as autism and schizophrenia." (PMID 35042901, 2022). "Numerous studies have thus provided evidence that disruption of SHANK3 is associated with autism and schizophrenia." (PMID 34188957, 2021). "The SNP rs9616915 was chosen because of its previously observed functional effects on SHANK3 expression in the hippocampus and because the SNP has previously been associated with autism." (PMID 34188957, 2021). "Germline disruption of the autism-linked gene Shank3 causes synaptic and autism-like behavioral deficits in young mice." (PMID 33616084, 2021). "Phelan-McDermid syndrome (PMS) is a rare genetic disorder compromising the 22q13 terminal region and affecting SHANK3, a gene crucial to the neurobehavioural phenotype and strongly linked to autism (ASD) and intellectual disability (ID)." (PMID 34246244, 2021). "In a first study, we studied social behavior and ultrasonic communication in a Shank3 deficient rat model for autism." (PMID 34072335, 2021). "In previous work, the rs9616915TT genotype has been associated with higher autism risk and reduced expression of SHANK3 mRNA in the human hippocampus." (PMID 34188957, 2021). "Another limitation is the possibility that some Shank3 mutations lead only to subtle or limited forms and symptoms in the autism spectrum and that are difficult to detect in mice (such as intellectual disabilities)." (PMID 33468258, 2021). "In humans, SHANK3 mutations lead to Phelan-McDermid syndrome and are one of the most penetrant causes of autism." (PMID 34072335, 2021). "Mutations affecting the synaptic-scaffold gene SHANK3 represent the most common genetic causes of autism with intellectual disability, accounting for about 1-2% of cases." (PMID 34188957, 2021). "HDAC inhibitors also showed significant therapeutic effects on behavioral deficits in the Shank3-deficient autism model via HSP regulation." (PMID 33994921, 2021). "The rs9616915 SNP was selected because it has been linked to autism and to SHANK3 expression in the hippocampus." (PMID 34188957, 2021). "These deficits appear to be more severe than related deficits displayed by established rat models for neurodevelopmental disorders, such as the Shank3 deficient rat model for autism." (PMID 34072335, 2021). "Another candidate gene located near SHANK3, and deleted in most cases of the syndrome, is the autism-linked gene IB2 (islet brain 2) that plays an important role in synaptic transmission and neuronal morphology." (PMID 33407854, 2021). "The gene SHANK3 in particular exhibits notable effects on autism risk, with large-effect mutations being responsible for an estimated 1-2% of cases, especially in conjunction with intellectual disability." (PMID 34188957, 2021). "Mutations in SHANK3 or changes in protein levels are associated with neurodevelopmental disorders, such as Phelan-McDermid syndrome, autism, and schizophrenia." (PMID 32273901, 2020). "The human SHANK3 gene was among the first genes encoding a synaptic protein which was shown to be affected in autism cases." (PMID 33115499, 2020). "The disruption of the Shank3 gene in mice (a mutation found in some cases of autism and intellectual disability) is linked to alterations in glutamatergic synapses and autistic-like behaviors." (PMID 32760255, 2020). "Mutations in the SH3 and multiple ankyrin repeat domains 3 (SHANK3) gene are associated with autism and affect the morphology of dendritic spines and synaptic transmission." (PMID 32244359, 2020). "Moessner R., Marshall C.R., Sutcliffe J.S., Skaug J., Pinto D., VincentJ., Zwaigenbaum L., Fernandez B., Roberts W., Szatmari P.,Scherer S.W. Contribution of SHANK3 mutations to autism spectrumdisorder." (PMID 33659799, 2020).